AKT2 (AKT serine/threonine kinase 2)
Diseases named in the same sentence as AKT2 in open-access papers (continued):
Sharing a sentence is not in itself a finding about the gene and the disease.
tumor (continued). "Akt1 KD had the highest (p<0.05), while Akt2 KD had the lowest (p<0.05) incidence of tumor cell apoptosis, while Akt3 KD tumors had less apoptosis than Akt1 KD tumors, but more than Akt2 KD." (PMID 27533079, 2016). "Akt1 KD mice had the lowest (p<0.05) tumor microvessel density, while tumors generated with Akt2 KD cells had the highest density of blood vessels." (PMID 27533079, 2016). "Our results demonstrate a key role of a new regulatory circuitof E2/ERα/miR-124/AKT2 in mediating tumor angiogenesis and cancer progression in BC." (PMID 27175587, 2016). "In agreement with the results in vitro, overexpression of miR-124 suppressed AKT2 expression, in tumor tissues." (PMID 27175587, 2016). "It is also possible that alterations in glucose homeostasis contributed to the enhanced tumor burden observed in Akt2 null mice." (PMID 26654940, 2016). "Tumors generated with Akt1 KD ID8 cells had significantly (p<0.05) lower tumor cell proliferation compared to control or Akt2 or 3 KD tumors." (PMID 27533079, 2016). "In our in vivo model, we found an increase in tumor cell proliferation in Akt3 knockdown tumors compared to controls, but again this increase was significantly less than that seen in Akt2 KD tumors." (PMID 27533079, 2016). "Conversely, tumor cell Akt2 knockdown resulted in significantly increased tumor size, metastasis and decreased survival time." (PMID 27533079, 2016). "Ablation of Akt3, both in tumor cells and in the host often led to results that were intermediate between Akt1 and Akt2 knockdown." (PMID 27533079, 2016). "Taken together, these findings demonstrate that miR-615-5p regulates AKT2 expression and functions as a tumor suppressor in PDAC development." (PMID 25856297, 2015). "Akt2 was also demonstrated to be strongly involved in the migration of NSCLC-derived disseminated tumor cells." (PMID 26234648, 2015). "AKT2 protein expression was elevated in tumor tissues compared with adjacent normal tissues, and further increased with the degree of tumor differentiation." (PMID 25856297, 2015). "However, mutation analysis from a single patient has identified an activating mutation in PIK3CA from the primary tumor, and RNA-seq datasets demonstrated overexpression of AKT2 mRNA in one of two areas of recurrence, perhaps suggesting that this pathway may be an important area for future research." (PMID 26793165, 2015). "Our results are in agreement with the large majority of studies suggesting that Akt2 plays a major role in cancer cell proliferation and consequently in tumor growth." (PMID 26234648, 2015). "The growth curve of different experimental groups also showed that tumors with high expression of miR-612 obtained the characteristic of slow growth and AKT2 rescued the impaired tumor growth." (PMID 26158514, 2015). "AKT2 amplification was detected only in the metastatic tumor samples, as part of a broad low level amplification event (0.4 log2 ratio, 2.5Mb comprising more than 75 genes/transcripts)." (PMID 25970776, 2015). "Based on the in vitro data showing that both Akt2-shRNA1 and Akt2-shRNA2 significantly inhibited cells’ proliferation and colony growth, we decided to use only one cell line in vivo in order to verify the impact of Akt2 silencing on tumor growth." (PMID 26234648, 2015). "Tumor tissues from nude mice of the LV-miR-615-5p-MIA group showed a significant decrease in AKT2 protein expression as well, compared with the LV-control-MIA group." (PMID 25856297, 2015). "Selective silencing of Akt2 reduced LNM35 tumor volume by 23.7% (2810.1 mm3 +/−687.4, p = 0.29), compared with LNM35 cells transfected with control-siRNA (3683 mm3 +/−405.6) as measured five weeks after tumor cell injection." (PMID 26234648, 2015). "In current study, we not only confirmed the tumor suppressor function of let-7b/g but also revealed a novel functional target of let-7 family, AKT2, together with the dysregulated signaling pathway, AKT2-mTOR-pS6." (PMID 25288334, 2014).
tumor (continued). "The inhibitory effect of tumour growth by miR-137 restoration, which can be abrogated by AKT2 overexpression, was also demonstrated using bioluminescence." (PMID 24970808, 2014). "More importantly in primary samples, AKT2 mRNA expression showed a negative correlation with let-7b/g expression, suggesting that let-7b/g exerts its tumor suppressor function in gastric carcinogenesis at least by partly down-regulating AKT2." (PMID 25288334, 2014). "Note that Akt1 is more highly expressed in ATII cells, which are the putative tumor originating cells, whereas Akt1 and Akt2 are expressed at near equivalent levels in Clara cells, which are not susceptible to transformation." (PMID 24722238, 2014). "Further investigations showed that miR-137 exerted its anti-tumour activity via inhibiting the AKT2/mTOR pathway." (PMID 24970808, 2014). "siRNA-mediated AKT2 knockdown was therefore performed to investigate if AKT2 downregulation phenocopied the tumor-suppressive effect of let-7b/g." (PMID 25288334, 2014). "This analysis revealed that, at both early and late time points, AJEJJenv infected Akt2−/− mice harbored significantly greater numbers of hyperplastic foci/tumors than WT, Akt1−/− and Akt3−/− mice, suggesting that ablation of Akt2 enhances tumor initiation." (PMID 24722238, 2014). "Of the few studies that have investigated the effect of Akt2 isoform ablation on tumor initiation and progression, only in mouse models of Neu- and PyMT-driven mammary carcinogenesis was Akt2 identified as a putative tumor suppressor." (PMID 24722238, 2014). "Short interfering RNA (siRNA) mediated knockdown of AKT2 phenocopied the tumor-suppressive effects of let-7b/g." (PMID 25288334, 2014). "Consistent with this in vitro data, re-expression of AKT2 markedly reversed the suppression of tumour growth induced by miR-137." (PMID 24970808, 2014). "In our MTB-IGFIR transgenic mice, we found that Akt1 or Akt2 ablation significantly increased in tumor latency and decreased tumor growth rate." (PMID 23919516, 2013). "Seventy-four primary tumour samples were analyzed for Akt1, Akt2, pAkt Thr308 and pAkt Ser408 expression and scored." (PMID 22842582, 2012). "We also determined the anti-tumor activity of BEZ235 and/or PS against tumor growth of subcutaneously implanted primary PDAC heterotransplants (possessing K-RAS mutation and AKT2 amplification) in the nude mice." (PMID 23232026, 2012). "There was an interesting trend to a longer time to progression in patients whose tumours had strong expression of total Akt2 or activated Akt (pAkt) detectable in both the cytoplasm and nucleus." (PMID 22842582, 2012). "The recovered c-DNA was additionally multiplex tested for three EMT markers [TWIST1, Akt2, phosphoinositide kinase-3 (PI3Kα)] and separately for the tumor stem cell marker ALDH1." (PMID 22264265, 2012). "The aim of this study is to investigate the association between AKT2 and the clinical outcome of non-small cell lung cancer (NSCLC) patients by detecting its expression levels in the tumor tissue samples." (PMID 21569643, 2011). "It has been revealed that AKT2 play a central role in tumorigenesis, tumor growth as well as metastasis." (PMID 21569643, 2011). "pAkt expression was detected in all tumor samples with only 2 cases showing rare positive cells, whereas Akt2 expression was found in 14 out of 35 BCC (40%); in particular in HPV positive samples over-expressing p16INK4a." (PMID 22082146, 2011). "Previous results showed that API-2 inhibits Akt2 activation and harbors anti-tumor activity against tumors with activated Akt." (PMID 20140245, 2010).
tumor (continued). "The recovered c-DNA was additionally multiplex tested for three EMT markers [Twist1, Akt2, PI3Kα] and separately for the tumor stem-cell markers ALDH1." (PMID 19589136, 2009). "Abnormalities in the PI3K/AKT pathway, including AKT2, contribute to tumor progression." (PMID 42196210, 2026). "Consequently, Akt2-overexpressed CTLs displayed reduced T-cell exhaustion within the tumor microenvironment and efficiently eradicated tumors." (PMID 40139836, 2025). "We then investigated whether Akt1 or Akt2 signaling also enabled the tumor-specific CTLs to overcome TME in the oncogene-induced HCC mouse model." (PMID 40139836, 2025). "Although we did not examine concordance of results in the liquid versus the tissue biopsy cohort for alterations in genes other than PIK3CA, PTEN, AKT1, AKT2, and AKT3, our results support the value of blood-based NGS panel testing in providing a comprehensive tumor mutational landscape." (PMID 40597213, 2025). "MiR‐29b has been demonstrated to suppress tumor growth by targeting the AKT2 isoform." (PMID 38225865, 2024). "However, it is generally accepted that AKT1 plays an important role in the early stages of tumor development (tumor initiation and proliferation), while AKT2 primarily assists in tumor metastasis." (PMID 39057065, 2024). "Similarly, an miRNA targeting AKT2, miR-200c, reduced tumor cell proliferation in both ER+ and ER– cell lines." (PMID 38543182, 2024). "However, only one gene, AKT2, presented a significant increase in tumor tissue (p = 0.01), and four genes showed a significant increase in normal tissue (AKT2, AKT3, PPARG, and PTEN; p ≤ 0.04)." (PMID 38505269, 2024). "Among the PIK3CA mutation-positive tumor samples with AKT data (CB n = 7, NCB n = 5), the amount of AKT present per 10 μg total protein ranged from 0.6 to 4.5 fmol for AKT1 and 0.6 to 2.0 fmol for AKT2." (PMID 38954770, 2024). "Firstly, the underlying mechanism of the identified ARGs, especially AKT2 and DAPK1, in tumor immune microenvironment and OV progression remained largely unknown, which needs further investigation." (PMID 38310291, 2024). "Therefore, in our research, we comprehensively evaluated and validated an anoikis-related signature (including AKT2 and DAPK1), which was associated with tumor immune microenvironment and sensitivity to immunotherapy/ chemotherapy." (PMID 38310291, 2024). "Overexpression of AKT1 and AKT2 are frequent events in BC that enhance tumor cell survival." (PMID 39796647, 2024). "Additionally, AKT2 protein expression was suppressed, and this inhibition of AKT2 was enhanced by miR-137 overexpression, suggesting a role for miR-137 in regulating AKT2-induced apoptosis and increasing tumour sensitivity to cisplatin." (PMID 39247624, 2024). "Besides, according to qRT-PCR assay, sh-circ_0000118 significantly upregulated miR-211-5p and miR-377-3p in the xenograft tumor tissues, but decreased the expression level of AKT2." (PMID 36719624, 2023). "Consistently, a previous study showed that AKT2 level was increased in CC tumor samples." (PMID 36719624, 2023). "Downregulation of miR-497-targeted AKT2 might affect tumor growth and chemoresistance to cisplatin in NSCLC." (PMID 37415224, 2023). "In order to understand the potential stages of metastatic dissemination for which AKT2 may be most critical, we explored extravasation from blood vessels and tumor cell proliferation at seeded distant sites as two candidate stages for the study of metastasis." (PMID 37894325, 2023). "In this context, platelet horizontal miR-126-3p transfer and subsequent downregulation of PIK3/AKT2 signaling may be clinically relevant, especially for hypothesizing the future management of MV production and selective delivery to tumor cells." (PMID 35628294, 2022).
tumor (continued). "In bladder cancer cell lines, Cur induced tumor suppressor miRNA, miR-203, DNA hypermethylation of the miR-203 promoter, hypomethylation of the miR-203 promoter, upregulation of the miR-203 expression, and downregulation of miR-203 target genes Akt2 and Src." (PMID 35327559, 2022). "Moreover, inhibition of β-catenin/AKT2-stimulated pyrimidine synthesis axis preferentially repressed β-catenin mutant cell proliferation and tumor formation." (PMID 36122209, 2022). "Indeed, the increase in miR-126 content in BC cells (via platelet MV delivery) led to the inhibition of AKT2 expression, thus suppressing the invading potential of tumor cells." (PMID 35628294, 2022). "The expression of akt2-a may also help longevity and remove tumor cell incursion and metastasis in reproductive castes of R. chinensis." (PMID 36362447, 2022). "In addition, some proteins are involved in many life activities such as tumor cell proliferation and migration, such as serine/threonine kinase 2 (AKT2)." (PMID 36338621, 2022). "In tumor genomes, AKT2 alterations significantly co-occur with ARID1A alterations (OR = 2.0, FDR<0.1% in MSK-IMPACT cohort of 10,945 samples;52 replicated at OR = 1.4, FDR<0.1% in an independent TCGA pan-cancer cohort of 10,967 samples; analysis via cBioPortal53)." (PMID 35614096, 2022). "While the simulation of AKT2 overexpression reached attractors supporting tumor development by inhibiting apoptosis and activation of epithelial to mesenchymal transition (EMT), in silico knockout of TWIST1 prevents tumor-associated characteristics." (PMID 35465155, 2022). "The CNVkit SCNA analysis also highlights the potential importance of oncogenes (e. g., RCP, CD44, WT1, BCL2L2, and AKT2) and tumor suppressors (e. g., PRKCDBP) to TNBC etiology and metastatic progression, as significant amplicons/deleted regions harbor these genes." (PMID 35992833, 2022). "Interestingly, miR-612 levels are inversely correlated with HCC tumor size and stage, microvascular invasion, and intrahepatic metastasis, as well as the protein levels of AKT2 (AKT Serine/Threonine Kinase 2) and EMT biomarkers." (PMID 35205327, 2022). "Thus, the results showed that the inability of Akt2 inhibition to affect tumor growth and metastasis, and even to exacerbate them, is due to its systemic effect." (PMID 35578699, 2021). "This is in contrast to the cell autonomous deletion of Akt2, which inhibited tumor growth." (PMID 35578699, 2021). "In contrast, Toulany and colleagues showed that knockdown of Akt1 and to some extent Akt3, but not Akt2, inhibited cell proliferation and tumor growth in K-Ras-mutated MDA-MB-231 cells." (PMID 34298660, 2021). "To emulate drug therapy, we systemically deleted Akt1 or Akt2 after tumor onset." (PMID 35578699, 2021). "Moreover, the in vivo transfection with siRNA against STAT3 decreased the pace of the tumor growth, a process that was reversed by the expression of Akt2." (PMID 33670268, 2021). "There is also evidence for tumor suppressor function of AKT2." (PMID 33498407, 2021). "The function of Akt1 and Akt2 in tumor progression and metastasis is debatable." (PMID 34298660, 2021). "Together, our study uncovered the oncogenic role of KLF5-dependent lncRNA DANCR transcription in GC in vivo and in vitro, which implicates the miR-194/AKT2 axis in tumor growth regulation, and it may be a potential therapeutic target for human GC." (PMID 34548487, 2021). "Knockdown/inhibition of Akt2 inhibited metastatic potential of CSC and non-CSC by inhibiting the expression of TWIST or mTOR and high levels of Akt2 could be detected in circulating tumor cells in orthotopic mouse models." (PMID 34298660, 2021). "This points to the significant role of Akt2 in the growth of the tumor." (PMID 33670268, 2021). "Moreover, AKT2 is expressed highly in numerous types of tumor cells, and there is a strong correlation between the high expression of AKT2 and the development of the malignant tumors in the liver, pancreas and colon." (PMID 32252758, 2020).
tumor (continued). "To understand the potential mechanism of miR-497 in inhibiting tumor growth, we showed that miR-497 blocked the activation of AKT2 and regulated cell proliferation, cell migration, colony formation and increases chemosensitivity of H1299 cells to cisplatin by inhibiting AKT2." (PMID 33015042, 2020). "QRT-PCR was used to evaluate the expression of miR-124 and AKT2 in these tumor tissues." (PMID 32873299, 2020). "In Pten+/− mice, Akt1, but not Akt2, deficiency dramatically inhibited the development of a range of tumours." (PMID 33276499, 2020). "The results also confirmed that miR-124 overexpression could inhibit tumor growth by suppressing the expression of AKT2 in vivo." (PMID 32873299, 2020). "Therefore, the results of our current research illustrate the role of AKT2 as a tumor oncogene, promoting cell proliferation and metastasis in LUAD." (PMID 32873299, 2020). "Our findings suggest that the low expression of akt2-a in the primary reproductive castes may also prevent tumour cell invasion and metastasis." (PMID 32424344, 2020). "In NSCLC, AKT2 can affect tumor cell survival and chemotherapy sensitivity." (PMID 32873299, 2020). "In this experiment, treatment with the Akt2 or Akt1/2 inhibitor plus DEX shows a significant anti-leukemic effect with reduced tumor size and prolonged overall survival of mice when compared with DEX alone, while treatment with the Akt1 inhibitor plus DEX did not achieve these results." (PMID 30598523, 2019). "Indeed, studies in neuroblastoma showed that S6K1 fails to modulate GLI1 activity, and, surprisingly, GLI1 acts as tumor suppressor in this context and its tumor-suppressive functions are inhibited by AKT2." (PMID 31244888, 2019). "The reason why AKT2 deficient mice facilitate tumor progression might be a hyperglycemic setting and therefore a heightened metabolism in the tumor cells due to the regulation of GLUT1 by AKT2." (PMID 31752925, 2019). "Interestingly, in orthotopic tumor mouse models, high expression levels of AKT2 were detected in circulating tumor cells (CTC)." (PMID 31357505, 2019). "Furthermore, a high level of AKT2 expression was observed also in circulating tumor cells (CTCs) in vivo." (PMID 31357505, 2019). "Similarly, AKT1 activation decreases tumor metastatic dissemination but promotes mammary tumorigenesis in mouse models, whereas AKT2 primarily increases tumor metastasis in those models." (PMID 30012111, 2018). "The authors could link differences in polarity and hydropathy values of the pleckstrin homology domain and the regulatory domain between the Akt isoforms to the tumor-promoting effects of Akt2 and Akt3." (PMID 29562639, 2018). "AKT1 and AKT2 genes enhance tumor growth by promoting epithelial-to-mesenchymal transition (EMT) through PI3K activation, and the tumor suppressor gene of the PTEN antagonist PI3K/AKT pathway induces AKT-regulated tumor metastasis through loss-of-function mutations." (PMID 28961226, 2017). "Importantly, induction of AKT1 knockdown slowed xenograft tumour growth, whereas AKT2 knockdown resulted in a striking regression of tumour size suggesting decreased tumour survival capacity." (PMID 28082369, 2017). "However, transgenic mammary expression of AKT1 or AKT2 alone in wild-type mice is insufficient to promote de novo tumour formation." (PMID 28082369, 2017). "Because mutations in the PI3K/Akt pathway located in AKT1, AKT2, AKT3, PTEN, and PIK3CA were analyzed altogether, their results did not provide any direct insights on the association between PIK3CA mutation status and primary tumor location." (PMID 29207615, 2017). "Animal models also demonstrated that let-7a inhibited tumor growth by targeting AKT2." (PMID 29050238, 2017). "The Akt family comprises three members (Akt1, Akt2, and Akt3) that share significant overall homological and kinase domain similarities but diverge in the linker region and the PH domain; they play distinct roles in development and tumor formation." (PMID 26993778, 2016).